STAT3 (signal transducer and activator of transcription 3)
Diseases named in the same sentence as STAT3 in open-access papers (continued):
Sharing a sentence is not in itself a finding about the gene and the disease.
bladder cancer (231 papers, 2006 to 2026). "In SMARCB1-deficient bladder cancer, STAT3 was significantly activated and facilitated tumor growth and metastasis." (PMID 39995416, 2025). "Overexpression of the regulator Musashi-2 has been linked to JAK2/STAT3 activation in 34% of bladder cancer samples." (PMID 40277814, 2025). "The nexus between mTOR and STAT3, and their association with adverse outcomes in patients with bladder cancer exhibiting elevated expression of both, is corroborated through comprehensive molecular analyses." (PMID 38886756, 2024). "Here, the authors show in several preclinical models that targeting IL6/JAK/STAT3 molecular pathway is a potential therapeutic approach for SMARCB1-deficient bladder cancer." (PMID 38355560, 2024). "The patient survival data analysis results predicted mTOR and STAT3 as the most associated with bladder cancer." (PMID 38886756, 2024). "Overall, these findings support the clinical evaluation of STAT3 inhibitors for the treatment of SMARCB1-deficient bladder cancer." (PMID 38355560, 2024). "This experiment submits that further investigation into mechanisms underlying β-AR-mediated STAT3 regulation by Foxp1 will cast new light upon the Warburg effect of therapeutic strategies for bladder cancer." (PMID 37663229, 2023). "PLCε was found to be upregulated in bladder cancer and caused the stimulation of STAT3 phosphorylation, which regulates the transcription of LDHA and, as a result, affects glucose consumption and lactate production." (PMID 36230984, 2022). "We suppose that the relation between STAT3 expression and bilharzial association was altered by the fact that most cases of bladder cancer that were associated with bilharziasis were of squamous carcinoma variant; which is almostly invasive in nature." (PMID 32102537, 2020). "Here we identify Signal transducer and activator of transcription 3 (Stat3)e as a Blcap interacting partner in bladder cancer and show that Blcap nuclear expression is associated with Stat3 expression." (PMID 29190807, 2017). "EGFR and IL6 are upstream regulators of STAT3, and all have been implicated in basal breast and bladder cancers." (PMID 27845906, 2016). "Elevated expression of STAT3 is also linked to proliferation and invasion of bladder cancer." (PMID 38455086, 2023). "STAT3 is also implicated in process of EMT in bladder cancer." (PMID 36230984, 2022). "In bladder cancer, neutrophils were associated with the formation of a premetastatic niche in tumor-free lymph nodes, and neutrophil infiltration was reported to be STAT3 mediated." (PMID 34205654, 2021). "The activation of the JAK-STAT3 pathway may be responsible for the growth and survival of bladder cancer cells, while the STAT3 silencing may cause the suppression of T24 bladder cancer cell proliferation." (PMID 33923108, 2021). "STAT3 overexpression is associated with a poor prognosis of bladder cancer." (PMID 27564099, 2016). "Moreover, STAT3 activation has been shown a role in predisposing urothelial basal cells toward the CIS progression pathway into invasive bladder cancer." (PMID 23637926, 2013). "Furthermore, long-term nicotine exposure-induced chemoresistance is associated with activation of STAT3, and inhibition of STAT3 by siRNA or a specific inhibitor restored chemosensitivity in bladder cancer cells." (PMID 22811589, 2012). "The increased apoptotic caspase activation implicated that apoptosis could be one of mechanisms underlying the decreased cell viability in bladder cancer cells in that Stat3 pathway was compromised by treatment of rAd/Stat3 or STA-21." (PMID 18939995, 2008). "These together suggested that bladder cancer cell death associated with inhibition of Stat3 pathway might have occurred." (PMID 18939995, 2008).
bladder cancer (continued). "In addition, activated STAT3 signalling may predispose urothelial basal cells toward the progression into invasive bladder cancer." (PMID 33923108, 2021). "Moreover, STAT3 activation was associated with bladder cancer cell growth and survival." (PMID 30744595, 2019). "Moreover, Bcl2 and Bcl-XL, as pro-survival genes directly transcripted by STAT3, were also repressed by metformin, suggesting that down-regulaiton of STAT3/Bcl2/Bcl-XL signaling pathways in metformin-treated bladder cancer cells caused increased apoptotic cell death." (PMID 26245871, 2015). "Therefore, we investigated whether metformin suppressing progression of precancerous lesions to invasive cancers in the MUN-induced rat bladder cancer model was associated with inhibition of STAT3 activation." (PMID 26245871, 2015). "To explore whether Stat3 activation is associated with cell growth and survival of bladder cancer, we targeted the Stat3 signaling pathway in bladder cancer cells using an adenovirus-mediated dominant-negative Stat3 (Y705F) and a small molecule compound, STA-21." (PMID 18939995, 2008). "CircRPPH1, a non-coding RNA exhibiting tissue-specific expression patterns, accelerates bladder cancer proliferation and migration by upregulating the STAT3 signaling pathway." (PMID 40635786, 2025). "In bladder cancer, miR-125b functions as a tumor suppressor by post-transcriptionally regulating IL-6R and STAT3 through direct interaction with their 3′ untranslated regions (3′-UTRs)." (PMID 41179679, 2025). "While direct mutations in the STAT3 gene itself are relatively rare, alterations in genes like FGFR3, a frequently mutated gene in bladder cancer, can indirectly lead to STAT3 activation." (PMID 40635786, 2025). "The binding of PD-L1 to integrinβ4/integrinβ6 triggers the AKT/GSK3β and STAT3 pathway respectively, resulting in the promotion of glycolysis in cervical and bladder cancer cells." (PMID 39897050, 2025). "In summary, our findings provide a novel immunotherapeutic strategy against bladder cancer through targeting the ETS1-PLA2G7-STAT1/STAT3-PD-L1 axis." (PMID 40169540, 2025). "The CXCL14/CCR7/STAT3 axis critically mediates cisplatin resistance in bladder cancer through dual modulation of DNA repair and glycolytic metabolism." (PMID 40898244, 2025). "Several natural products have also been identified as potential inhibitors targeting the STAT3 pathway in bladder cancer." (PMID 40635786, 2025). "In bladder cancer, it promotes oncogenesis through STAT3 pathway activation, and in triple-negative breast cancer, it confers radioresistance via regulation of non-homologous end joining." (PMID 41208974, 2025). "One study showed that low SMARCB1 expression promoted Bladder cancer growth by activating STAT3; therefore, targeting the IL6/JAK/STAT3 pathway is a potential treatment for SMARCB1-deficient tumors." (PMID 40115023, 2025). "In summary, our study suggests that ETS1-mediated overexpression of PLA2G7 can regulate the phosphorylation of STAT1 and STAT3, leading to PD-L1 overexpression and promoting immune evasion in bladder cancer." (PMID 40169540, 2025). "Taken together, our results suggest that disrupting the CXCL14/CCR7/STAT3 signaling axis, both in vitro and in vivo, enhances DNA damage and increases cisplatin sensitivity in bladder cancer." (PMID 40898244, 2025). "On one hand, EP300 loss-of-function relieves its inhibition on IL-1α signaling, activating the IL-6/JAK/STAT3 pathway and driving bladder cancer." (PMID 40375990, 2025). "The overexpression of the mitotic kinase BUB1 has been implicated in the initiation and progression of various cancers, including bladder cancer, by mediating the STAT3 signaling pathway." (PMID 40635786, 2025). "Study have demonstrated that absence of SMARCB1 (encoding SNF5/BAF47 protein) leads to enhanced chromatin accessibility at the STAT3 promoter, which in turn triggers activation of the IL6/JAK/STAT3 pathway to facilitate the growth and spread of bladder cancer." (PMID 39779467, 2025).
bladder cancer (continued). "Our previously published studies demonstrated that activation of the IL6/STAT3 pathway plays a major role in the induction of cell motility, especially in MØs and bladder cancer cells." (PMID 40807456, 2025). "Our results demonstrated that the CXCL14/CCR7/STAT3 axis significantly promotes the glycolytic shift in bladder cancer cells by upregulating the expression of HK2 and LDHA, two key glycolytic enzymes." (PMID 40898244, 2025). "Mechanistically, CAF-secreted CXCL14 engaged CCR7 on bladder cancer cells, triggering STAT3 phosphorylation and consequently upregulating the DNA repair gene ERCC4 to promote cisplatin resistance." (PMID 40898244, 2025). "Conversely, FTO plays a positive role in bladder cancer by maintaining STAT3 mRNA stability through decreasing its m6A modification levels." (PMID 40244180, 2025). "The STAT3 inhibitor TTI‐101 can inhibit the growth and metastasis of SMARCB1‐deficient bladder cancer." (PMID 39779467, 2025). "Given the pro-survival action and oncogenic role of STAT3 in bladder cancer, we explored the role of STAT3 in Fucoxanthin’s proapoptotic effect on these cells." (PMID 39997178, 2025). "LncUCA1 activates mTOR, by inducing signal transducer and activator of transcription 3 protein, and inhibiting miR-143, thereby upregulating hexokinase 2 and glycolysis in bladder cancer." (PMID 38544804, 2024). "Simultaneous inhibition of both PI3K and STAT3 with small-molecule inhibitors resulted in sustained tumor regression in patient-derived bladder cancer xenografts." (PMID 39068158, 2024). "The activation of STAT3 is the key to the differentiation of macrophages to the M2 phenotype, and the expression of M2-type signature genes promotes bladder cancer cell invasion and migration." (PMID 38523627, 2024). "GSDMB, a member of the gasdermin protein family participating in the provoking of pyroptosis, has been proven to promote the progression of bladder cancer by activating the signal transducer and activator of transcription 3 (STAT3)." (PMID 38695942, 2024). "proved that nicotine stimulates the cell proliferation of bladder cancer cells via the activation of Stat3 and ERK1/2 pathway." (PMID 39742262, 2024). "To further investigate the mechanism by which CENPW knockdown inhibits bladder cancer, we conducted a comparative analysis of the protein levels of STAT3 and P-STAT3 in both the si-NC group and si-CENPW group of 5637 and UM-UC-3 cells." (PMID 38213721, 2024). "IGF2BP3-mediated mRNA stability of multiple oncogenes, such as CDK2 and STAT3 via a m6A-dependent manner, have been found to promote the development of bladder cancer." (PMID 39680264, 2024). "Through GSEA analysis and RNA sequencing, we found that the JAK/STAT3 pathway is activated in basal bladder cancer and in RC48-exposed SW780 cells." (PMID 39840049, 2024). "mTOR and STAT3 were selected as the two gene targets for a knockdown in our pilot system based on bladder cancer patient data." (PMID 38886756, 2024). "BUB1 regulates STAT3 signalling through transcriptional activation to facilitate bladder cancer progression and proliferation." (PMID 38498903, 2024). "In TCGA, GEO, and CCLE datasets, we also observed that the expression of STAT3 and pSTAT3 is lower in luminal bladder cancer than in basal bladder cancer." (PMID 39840049, 2024). "Specifically, patients with bladder cancer having lower levels of mTOR and STAT3 were predicted to have a longer survival compared to those with high mTOR and STAT3 levels." (PMID 38886756, 2024). "Through the regulation of EMT, miR-98 suppresses EMT and metastasis, as observed in bladder cancer, where it targets the IL-6/STAT3 signaling pathway." (PMID 38872210, 2024). "Hsa_circ_0068871 targets miR-181a-5p, leading to upregulation of FGFR3 expression and ultimately promotes STAT3 signaling in bladder cancer progression." (PMID 38245798, 2024).
bladder cancer (continued). "The mTOR/STAT3 double knock-down diminished cell viability in two distinct bladder cancer cell lines at half the concentration of each siRNA compared to single targeting of each gene." (PMID 38886756, 2024). "This showcases a complex regulatory interaction between SNHG16, miR-98, and STAT3, influencing the Wnt/β-catenin pathway and bladder cancer development." (PMID 38872210, 2024). "This can be explained by the fact that GSDM B binds to STAT3, thereby activating STAT3 signalling and modulating glucose metabolism and increasing its phosphorylation in bladder cancer." (PMID 39766111, 2024). "Lastly, the upregulation of SNHG16 in bladder cancer was revealed; it negatively regulates miR-98 expression, which contributes to bladder cancer malignancy through the miR-98/STAT3/Wnt/β-catenin pathway axis." (PMID 38872210, 2024). "In the context of bladder cancer, cancer-associated fibroblasts (CAFs) secrete CXCL12, which activates the JAK2/STAT3 signaling pathway, leading to the accumulation of p62." (PMID 38920657, 2024). "Here, we demonstrate that SMARCB1 deficiency, defined as genomic SMARCB1 copy number loss associated with reduced mRNA, drives disease progression in patients with bladder cancer by engaging STAT3." (PMID 38355560, 2024). "EZH2 can promote the proliferation and migration of bladder cancer cells by activating JAK2/STAT3 signalling pathway." (PMID 38506082, 2024). "We selected the genes with a weight > 1 of JAK/STAT3 pathways and observed the mRNA expression in basal and luminal bladder cancer." (PMID 39840049, 2024). "This was supported by previous studies that found SOCS7 silencing promoted the nuclear translocation of STAT3 in bladder cancer cells." (PMID 39431622, 2024). "Activates mTOR, inducing signal transducer and activator of transcription 3 protein, and inhibiting miR-143, thereby upregulating hexokinase 2 and glycolysis in bladder cancer." (PMID 38544804, 2024). "Overall, the current study indicated sertindole exerts bladder cancer cytotoxicity by provoking apoptosis through targeted inhibition of the antiapoptotic STAT3/BCL-xL signaling axis." (PMID 37511611, 2023). "For example, the STAT3 pathway regulates the proliferation and migration of drug-resistant bladder cancer cells by regulating Cyclin D1 and MMP2." (PMID 36793374, 2023). "In bladder cancer cells, miR-145 expression inhibited STAT3 activation, stimulated FOXO1 expression, and suppressed cell growth." (PMID 37834058, 2023). "TSN IIA controls the STAT3/chemokine ligand 2 signaling pathway to prevent epithelial-mesenchymal transition in bladder cancer cells." (PMID 38146460, 2023). "The present study certainly unraveled the cytotoxic effect of sertindole on bladder cancer cells and the blockade of STAT3 signaling as an integral mechanism of action in this process." (PMID 37511611, 2023). "BUB1 plays a key role in chromosome arrangement during the spindle assembly checkpoint and mitosis and it promotes the initialization and development of bladder cancer by regulating the STAT3 signaling." (PMID 38053725, 2023). "Our current findings underscore the potential of using myeloid cell-targeted STAT3 inhibition to overcome resistance of genitourinary cancers, such as kidney and bladder cancers, to immunotherapy and trigger CD8 T-cell-mediated antitumor immune responses." (PMID 38259453, 2023). "In conclusion, Foxp1 promoted occurrence and development of bladder cancer through the Warburg effect by the activation of STAT3 activity and repressing β-AR transcription." (PMID 37663229, 2023). "Accordingly, the in vivo evidence of sertindole to retard bladder tumor growth and lower tyrosine 705-phosphorylated STAT3 levels within bladder tumors is indispensable to substantiating sertindole’s potential as an option for treating bladder cancer." (PMID 37511611, 2023). "In vitro and animal experiments have also found that silencing STAT3 has an inhibitory effect on bladder cancer." (PMID 38455086, 2023).
bladder cancer (continued). "Retinoic Acid-Related Orphan Receptor C regulates proliferation, glycolysis, and chemoresistance via the PD-L1/ITGB6/STAT3 signaling axis in bladder cancer." (PMID 37434177, 2023). "Our mechanistic inquiry identified BCL-xL downregulation as a critical mediator downstream of STAT3 inhibition for sertindole-induced bladder cancer cell apoptosis, as BCL-xL overexpression protected cells from sertindole’s proapoptotic action." (PMID 37511611, 2023). "As expected, the expression of MTHFD2 correlated positively with the expression of PD‐L1 (r = 0.7434, p = 0.001), and phosphorylation of JAK1 (r = 0.7926, p < 0.001) and STAT3 (r = 0.8613, p < 0.001) in bladder cancer tissues." (PMID 37480214, 2023). "BUB1 was found to modulate the G2/M transition to promote the proliferation of non-muscle-invasive bladder cancer cells and drove the progression and proliferation of bladder cancer by regulating the transcriptional activation of STAT3 signaling." (PMID 36787437, 2023). "Expectedly, Foxp1 promoted STAT3 activity to heighten the Warburg effect by β-AR in a model of bladder cancer." (PMID 37663229, 2023). "Mechanistically, we elucidated that sertindole induces apoptosis through targeted inhibition of the pro-survival STAT3/BCL-xL pathway in bladder cancer cells." (PMID 37511611, 2023). "β-AR inhibitor Oxprenolol hydrochloride (10 nM) induced p-STAT3 protein expression in bladder cancer cells." (PMID 37663229, 2023). "In bladder cancer, persistent activation of STAT3 is vital to sustain cell proliferation, promote survival, facilitate metastasis, and contribute to chemoresistance." (PMID 37511611, 2023). "While STAT3 transcription factor is well-known master regulator of tumor immune evasion, little is known about the role of STAT3 in the resistance of renal or bladder cancers to immunotherapy." (PMID 38259453, 2023). "Data presented here revealed sertindole as an inhibitor of STAT3 activation but also confirmed STAT3 blockage as an essential mechanism responsible for sertindole-induced apoptosis in bladder cancer cells." (PMID 37511611, 2023). "Given STAT3’s well-established prosurvival action and fundamental role in promoting bladder cancer genesis and progression, we examined sertindole’s effect on STAT3 activity in bladder TCC cells." (PMID 37511611, 2023). "Data presented here underscored that survivin downregulation due to STAT3 blockage by HME is a vital mechanism of HME’s cytotoxic action on bladder cancer cells." (PMID 36613579, 2022). "In vitro, STAT3 knockdown in bladder cancer cells inhibited cell proliferation, migration, and invasion." (PMID 36227136, 2022). "The protein level of STAT3 and p-STAT3 in bladder cancer tissues was higher than that in normal tissues, especially the strong staining signal of p-STAT3 in the nucleus." (PMID 36227136, 2022). "Overall, we argue that HME blocks STAT3 activation to downregulate survivin, in turn promoting bladder cancer cell death." (PMID 36613579, 2022). "Cancer-associated fibroblasts were reported to be involved in the process of bladder cancer progression, through the stimulation of STAT3 phosphorylation." (PMID 36230984, 2022). "Another study revealed that STAT3 can be a part of a process that facilitated doxorubicin resistance in bladder cancer." (PMID 36230984, 2022). "Given that SRC activation was inhibited in all HME-treated bladder cancer cell lines, we figured SRC is the primary target of HME for blocking STAT3 activation, in turn promoting bladder cancer cytotoxicity." (PMID 36613579, 2022). "Taken together, SENP3 protein level is up-regulated in bladder cancer, which is correlates with protein expression of STAT3 and p-STAT3." (PMID 36227136, 2022). "The results showed that the expression levels of SENP3, STAT3 and p-STAT3 in bladder cancer tissues were higher than para-cancerous normal tissues." (PMID 36227136, 2022).